RN7SL308P (RNA, 7SL, cytoplasmic 308, pseudogene)
Gene: Miscellaneous RNA gene on chromosome 8 (80,776,666 to 80,776,962, reverse strand). Ensembl gene ENSG00000243951.
Homologues: Orthologues: chimpanzee Metazoa_SRP (98% identical), macaque Metazoa_SRP (93% identical). Paralogues in human: RN7SL1 (83% identical), RN7SL296P (83% identical), RN7SL2 (82% identical), RN7SL3 (81% identical), RN7SL664P (80% identical), RN7SL322P (80% identical), RN7SL126P (79% identical), RN7SL130P (79% identical), RN7SL186P (79% identical), RN7SL187P (79% identical), RN7SL218P (79% identical), RN7SL44P (79% identical), and 699 more.